SOCS3 (suppressor of cytokine signaling 3)
Diseases named in the same sentence as SOCS3 in open-access papers (continued):
Sharing a sentence is not in itself a finding about the gene and the disease.
Insulin resistance (continued). "Expression of SOCS-3 amplifies along with the increase in fat mass and abdominal adiposity during aging, as well as an increase in insulin resistance, suggesting that it could be a mediator of leptin resistance in aging individuals." (PMID 24455217, 2013). "The mechanism whereby excessive FFAs in the blood induce insulin resistance is partly through the mediation of protein kinase C, resulting in impaired function of insulin receptor substrate-1 (IRS-1), which further activates JNK and SOCS3, contributing to insulin resistance." (PMID 22278044, 2013). "We hypothesize that skeletal muscle SOCS3 contributes to obesity and insulin resistance by antagonizing leptin and insulin signaling." (PMID 23115649, 2012). "To determine whether up-regulation of muscle SOCS3 expression contributes to the development of obesity and insulin resistance, we generated a transgenic murine model for over-expressing SOCS3 in tissue specific manner." (PMID 23115649, 2012). "Therefore, SOCS3 is a single molecule that mediates both leptin and insulin resistance due to its ability to down-regulate leptin and insulin signaling." (PMID 23115649, 2012). "Also of note we found a normalization of local markers of insulin resistance in adipose tissue, such as SOCS3 and IRS1." (PMID 20543949, 2010). "However, it was observed that overnutrition-mediated activation of IKKβ/NF-κB was activated intracellularly by ER stress and prompted both hypothalamic leptin and insulin resistance through the induction of suppressor of cytokine signaling 3 (SOCS3), an inhibitor of leptin and insulin signaling." (PMID 34957242, 2021). "Both TNF-α and SOCS3 may increase insulin resistance via differing possible scenarios." (PMID 31940889, 2020). "Another is a more indirect scenario by way of TNF-α via stimulating SOCS3 and in turn SOCS3 through affecting the insulin receptor substrate complex leading to the inhibition of the insulin/insulin receptor-mediated pathway, finally resulting in increased adipocyte insulin resistance." (PMID 31940889, 2020). "In addition to being adaptor proteins that act as negative regulators of cytokine and growth factor signaling, the proteins of the suppressor of cytokine signaling (SOCS), in particular SOCS1 and SOCS3, negatively regulate the insulin signaling, linking the cytokine signaling to insulin resistance." (PMID 29535681, 2018). "Similarly in a SOCS3 cKO mouse model, salicylate partially improved insulin resistance." (PMID 25874611, 2015). "This suggests that AXL may drive increased expression of SOCS3, which has been implicated in genotype 1 mediated insulin resistance and treatment non-response." (PMID 26313459, 2015). "In addition to SOCS3, the lipid-dependent kinases, PKC family has been reported to inhibit several components of the insulin signaling pathway, among the 10 isoforms, PKCε is the isoform most often implicated in association with hepatic insulin resistance." (PMID 25160038, 2014). "The SOCS3 connection between IL-6 and insulin signaling could be an explanation to the observation that mice, when infused with high doses of IL-6 (0.5 μg/h), induced insulin resistance in skeletal muscle." (PMID 22761857, 2012). "Taken together, accumulating evidence strongly suggests that a single molecule, suppressor of cytokine signaling 3 (SOCS3), may mediate both leptin and insulin resistance due to its ability to inhibit leptin and insulin signaling in both central and peripheral target tissues." (PMID 23115649, 2012). "Although over-expression of SOCS3 in adipose tissue causes local insulin resistance, it is not sufficient to cause systemic insulin resistance, maybe due to the limited contribution of adipose tissue in whole-body glucose disposal." (PMID 23115649, 2012).
Insulin resistance (continued). "IL-6 contributes to insulin resistance through a complementary mechanism by activating the signal transducer and activator of transcription 3 (STAT3) pathway, which induces suppressor of cytokine signaling-3 (SOCS-3) expression." (PMID 41403736, 2025). "The transcription of SOCS3, induced by NF-κB, leads to the degradation of IRS1/2 via the proteasome, exacerbating insulin resistance." (PMID 41010046, 2025). "Functional enrichment analysis showed that SOCS3, IL6, FOXO1, CEBPB, SOX9, and PPARGC1A were mainly involved in the adipocytokine signaling pathway, insulin resistance, FoxO signaling pathway, AMPK signaling pathway, and PI3K-Akt signaling pathway." (PMID 38415055, 2024). "TNF-α, IL-6, and leptin activate inhibitory molecules such as the suppressor of cytokine signaling 3 (SOCS3) and c-Jun NH2-terminal kinase (JNK) that suppress insulin signaling, thus resulting in insulin resistance." (PMID 38397916, 2024). "Socs3 can be induced by certain inflammatory cytokines (e.g., TNFα and IL6) to contribute to inflammation-mediated insulin resistance in the liver and adipose tissue." (PMID 36709676, 2023). "GJA1 was found interacting with a suppressor of cytokine signaling 3 (SOCS3) and other proteins involved in the mechanism leading to tumor progression through insulin resistance-related pathways." (PMID 37529379, 2023). "The mechanism of IL-6-induced insulin resistance in the liver involves the activation of STAT3 and subsequent induction of the SOCS3 suppressor." (PMID 35052633, 2022). "Excessive chronic IL-6 production promotes the development of insulin resistance and T2D by impairing the phosphorylation of IR and IRS-1 via the upregulation of SOCS-3 (suppressor of cytokine signaling 3), a potential inhibitor of insulin signaling." (PMID 35629988, 2022). "IL-6 and SOCS3 mediate inflammatory responses and the satiety hormone of leptin, induce dysfunction of Jak-STAT signaling pathway, leading to insulin resistance and lipid metabolic disorders." (PMID 32106651, 2021). "This analysis confirmed that the liver of Hsp10 KD mice exhibited a molecular signature of insulin resistance with 40% increased S1101 and S632 phosphorylation of IRS1 and increased SOCS3 levels." (PMID 33946318, 2021). "SOCS3 is a key regulator of the JAK-STAT pathway, and studies have shown that SOCS3 plays a key role in leptin and insulin resistance." (PMID 32168898, 2020). "In order to begin delving into the mechanisms responsible for driving the synaptic insulin resistance in TBI animals observed in our study, we determined levels of SOCS3." (PMID 31160730, 2019). "Interleukin 6 (IL-6) is another inflammatory cytokine, strongly correlated with insulin resistance in the liver through JNK and via increasing the expression of SOCS3." (PMID 30096951, 2018). "Leptin and insulin resistance in the CNS can also result from overactivation of signal transducer and activator of transcription 3/suppressor of cytokine signaling 3 (STAT3/SOCS3), an intracellular pathway that is activated by leptin." (PMID 28592656, 2017). "Chronic activation of STAT3 has been reported to play a part in the development of insulin resistance by increasing the levels of SOCS1 and SOCS3 proteins." (PMID 28783714, 2017). "SOCS3 links the IL-6–STAT3 pathway to insulin signaling and plays a critical role in the development of insulin resistance in type 2 diabetes." (PMID 28706484, 2017). "As a cell surface receptor of RBP4, STRA6 activated JAK2-STAT5 signal pathway, induced production of SOCS-3 by combining with retinol-RBP4 complexes, and led to insulin resistance to promote the occurrence of T2DM." (PMID 27446956, 2016). "Serum levels of these cytokines correlate remarkably well with the presence of insulin resistance, and adipose tissue-derived TNF-α and IL-6 have been shown to regulate hepatic insulin resistance via upregulation of SOCS3, a suppressor of cytokine signaling." (PMID 27247565, 2016).
Insulin resistance (continued). "The possible link between HCV infection, insulin resistance, and the early phase of viral kinetics during antiviral treatment involves the downregulation of IRS1/2 and upregulation of the suppressor of cytokine signaling-3 (SOCS-3) genes in liver tissue." (PMID 25821463, 2015). "To elucidate the probably mechanism on the effect of insulin resistance HUVEC cells induced by miR-492, we characterized STAT3, SOCS3, and P-selectin expression in the insulin resistance HUVEC cells transfected with miR-492 mimics or pre-scramble for 48 h." (PMID 24526524, 2014). "Our findings of increased TNFα and SOCS3 in retinal endothelial and Müller cells under high glucose conditions agree well with findings in other cell types, including adipocytes and smooth muscle cells, suggesting that these retinal cells may also undergo a form of insulin resistance." (PMID 24695399, 2014). "In the current study, induced phosphorylation of JNK and up-regulated level of SOCS3 were reversed by the administration of SAMC, demonstrating the effectiveness of SAMC to suppress the process of FFAs-induced lipid imbalance, which might be one of the causal factors of insulin resistance." (PMID 22278044, 2013). "A gamma of results has shown that exercise training decreases molecules activity or protein levels that can lead to insulin resistance (PTEN, PTP1B, SOCS3, pro-inflammatory molecule, S-nitrosation, and others); it can also improve insulin resistance." (PMID 23046739, 2012). "Other well-characterized molecules that induce insulin resistance and are induced by the high-fat diet are the phosphatase protein, such as PTP, PTEN, and SOCS3." (PMID 23046739, 2012). "Ingestion of a HF diet induced a significant postprandial elevation of LPS, accompanied by an increased mononuclear cell expression of TLR-4, NF-ΚB and suppressor of cytokine signaling-3 (SOCS-3), an adipokine involved in insulin resistance." (PMID 22115311, 2011). "In vitro studies demonstrated that chronic exposure to IL-6 induces insulin resistance in skeletal muscle through induction of JNK, SOCS-3, and protein tyrosine phosphatase 1B." (PMID 21197447, 2010). "Furthermore, STA ameliorated insulin resistance, as evidenced by the upregulation of GLUT4 and IRS2 expression and the downregulation of PTP1B and SOCS3 expression." (PMID 40994455, 2025). "In recent years, researchers have found that SOCS3 is involved in the AMPK signaling pathway, insulin resistance, adipocytokine signaling pathway, and JAK/STAT pathway, is activated/triggered by leptin signals, and plays important roles in lipid metabolism processes." (PMID 38415055, 2024). "Insulin resistance may be due to the activation of Ser/Thr kinases; decreased expression of IRS-1, GLUT4 and PPARγ; or activation of suppressor of cytokine signaling 3 (SOCS3) in adipocytes." (PMID 38397072, 2024). "Recent studies have found an increase in SOCS3 expression in the hepatocytes of patients with NAFLD, which may be related to inflammation and insulin resistance in these conditions." (PMID 38549670, 2024). "Additionally, IL-6 induces the expression of a suppressor of cytokine signaling 3 (SOCS3), which degrades IRS-1, further worsening insulin resistance." (PMID 39458444, 2024). "IL-6 induces insulin resistance by reducing GLUT4 and IRS1 expression by activating the JAK-STAT (mediates cellular inflammatory response and cellular signals, such as insulin growth factor) and increasing SOCS3 expression." (PMID 38397916, 2024). "Moreover, SOCS3 ubiquitinates IRS-1 to induce its degradation, leading IL-6 to induce insulin resistance." (PMID 37555019, 2023). "IL-6 induces insulin resistance by downregulating insulin receptor substrate-1 (IRS-1) phosphorylation and transcription and by upregulating suppressor of cytokine signaling 3 (SOCS3), which inhibits insulin receptors." (PMID 37893164, 2023).
Insulin resistance (continued). "Insulin resistance, common co-existing with NAFLD, is contributed by inflammatory factors binding to IRS for ubiquitin-mediated degradation via the activation of Suppressors of Cytokine Signalling 3 (SOCS3)." (PMID 36035124, 2022). "A recent mechanistic study reported that overexpression of ANGPTL7 could upregulate SOCS3, which inhibited the phosphorylation of AKT, promoted ERK1/2 phosphorylation and ultimately led to insulin resistance and type 2 diabetic mellitus (T2DM) in mouse." (PMID 36078120, 2022). "Interestingly, the elevation of Socs3 in SAT and BAT at 30 weeks was consistent with the changes in whole-body insulin resistance seen at this time of prolonged HFD feeding." (PMID 34948432, 2021). "From the data obtained, an improved glucose utilization and AMPK phosphorylation and decreased Akt phosphorylation, suppressor of cytokine signaling 3 (SOCS-3) expression and janus kinase (JAK) expression ultimately resulting in the suppression of IL-6-induced insulin resistance was observed." (PMID 31718066, 2019). "MiR-16 has been reported to play a key role in regulation of insulin signaling through a reduction in TNFα and suppressor of cytokine signaling 3 (SOCS3) signaling and increase in insulin-like growth factor binding protein-3 (IGFBP-3) levels to inhibit insulin resistance." (PMID 29214180, 2017). "Therefore, we provide a novel finding that miR-15b and miR-16 play a role in preventing insulin resistance in REC cultured in high glucose, via reduced activation of TNFα and SOCS3 pathways and increased IGFBP-3 levels." (PMID 25888955, 2015). "In addition, increased levels of TNFα and SOCS3 lead to enhanced IRS-1 phosphorylation on serine 307, elevated IR (Tyr960), and decreased phosphorylation of IR (Tyr1150/1151), leading to insulin resistance and increased apoptosis." (PMID 25888955, 2015). "The reciprocal stimulation of SOCS3 and TNF-α expression suggests that positive feedback between these two factors could play an important role in mediating the development of insulin resistance and apoptotic cell death in rMC-1 cells." (PMID 25352752, 2014). "Rstn has been shown to confer glucose intolerance and insulin resistance, and although no receptor for Rstn has been identified, induction of SOCS3 intracellularly has been suggested as a potential mechanism by which Rstn inhibits insulin signaling." (PMID 22815920, 2012). "Overexpression of SOCS3 in muscle exacerbated diet-induced obesity and insulin resistance but this effect was not due to a decreased insulin signaling but to an alteration in muscle integrity leading to a reduction in locomotor activity and energy expenditure." (PMID 23316186, 2012). "Enhanced SOCS3 expression may prevent HCC development, but may induce insulin resistance, immune dysfunction, and refractoriness to IFN therapy." (PMID 20862390, 2010). "Furthermore, it mitigated insulin resistance by upregulating the expression of insulin‐sensitive factors, such as GLUT4 and IRS2, while concurrently downregulating insulin resistance factors, including PTP1B and SOCS3." (PMID 40994455, 2025). "Additionally, hesperidin demonstrated the ability to downregulate the expression of suppressor of cytokine signaling-3 (SOCS-3) and C-reactive protein (CRP) mRNA, both of which play pivotal roles in insulin resistance, and it also exhibited inhibitory effects on IL-6 production induced by LPS." (PMID 38234970, 2023). "ANGPTL7 was found to play a critical role in inducing insulin resistance, which occurred through multiple mechanisms involving the down regulation of Insulin receptor (INSR), upregulation of suppressor of cytokine signaling 3 protein (SOCS3) to degrade insulin receptor substrate 1 (IRS1)." (PMID 36017324, 2022). "However, although hepatocyte‐specific knockout of Il1r1 showed increased basal levels of hepatic SOCS3, we did not observe a spontaneous phenotype of insulin resistance or other metabolic perturbances in the knockout mice." (PMID 36101976, 2022).
Insulin resistance (continued). "The postprandial increase of plasma LPS observed after a high-fat meal increases the expression of NF-кB and a suppressor of cytokine signaling-3 (SOCS-3), which are involved in insulin resistance; no such changes are observed in the case of a diet rich in fiber and fruits." (PMID 34948234, 2021). "Interestingly, the deletion of SOCS3 in leptin receptor-expressing cells protects mice from HFD-induced systemic insulin resistance, without significant weight changes." (PMID 30875909, 2019). "In our study, both SOCS3 and PKCε were significantly increased with the development of NAFLD, which was consistent with the impairment of insulin signaling pathway, indicating these regulatory molecules may contribute to the insulin resistance." (PMID 25160038, 2014). "However, the role of SOCS3 in skeletal muscle, a key tissue contributing to obesity and insulin resistance, is not known." (PMID 23115649, 2012). "However, the effect of SOCS3 on insulin resistance in AD has not been defined." (PMID 29973864, 2018). "However, in the long term, leptin induces the expression of suppressor of cytokine signaling 3 (SOCS3), a negative feedback inhibitor that blocks STAT3 activation and contributes to leptin and insulin resistance in the context of obesity." (PMID 40872612, 2025). "NF-κB also activates the expression of the suppressor of cytokine signaling 3 (SOCS3) which promotes negative feedback in the insulin and leptin intracellular signaling pathways, potentially linking hypothalamic inflammation with central leptin and insulin resistance." (PMID 31057350, 2019).